MALAT1 (metastasis associated lung adenocarcinoma transcript 1)
Diseases named in the same sentence as MALAT1 in open-access papers (continued):
Sharing a sentence is not in itself a finding about the gene and the disease.
tumor (continued). "In accordance with this notion, current data showed that an RNase T1 treatment, relative to the MALAT1 knockdown, exhibits more prominent influence on PTBP1/PSF interaction in HEK293 cells and in a series of tumor cells." (PMID 36563164, 2022). "In breast cancer, a variety of non-coding RNAs have been found to work as tumor suppressors or tumor-promoting effectors, such as XIST, HOTAIR, GAS5, MALAT1, etc.." (PMID 36230738, 2022). "For example, MALAT1, which has carcinogenic effects, is the commonest lncRNA in lung cancer, which can promote NSCLC tumor growth and metastasis by regulating the miR124/STAT3 and miR204/SLUG axis." (PMID 35719401, 2022). "Knocking down MALAT1 or SEPT2, or elevating miR-503-5p mitigated the pro-tumor effects of upregulated JMJD2C on NSCLC." (PMID 35046387, 2022). "The p-values of tumor size from OS and PFS multivariate Cox analysis was less than 0.1, and the p-value of MALAT1 expression from PFS multivariate Cox analysis was less than 0.1." (PMID 36685103, 2022). "LncRNAs regulate EMT process by targeting EMT-related signalling pathways directly (i.e., H19, HOTAIR, ZEB2-AS1, LincRNA-p21 and SNHG1), or function as ceRNAs (i.e., H19, HOTTIP, MALAT1, SNHG1 and SNHG6) for tumour suppressive miRNAs." (PMID 36310592, 2022). "In particular, it serves as a tumor suppressor in diverse malignancies by targeting critical oncogenes or anti-oncogenes, including EZH2, DNMT3a, MALAT-1, ZEB1, and USP47." (PMID 35205710, 2022). "Using qPCR, we analysed the expression of DCN, miR-200c and five lncRNAs (LUCAT1, MALAT1, lncTCF7, XIST, and ZFAS1) in lymph node and liver metastases in comparison to the invasive front and central part of a primary tumour." (PMID 35052821, 2022). "Our results showed insignificant upregulation of DCN and significant upregulation for miR-200c, MALAT1, lncTCF7 and ZFAS1 in metastases compared to the primary tumour." (PMID 35052821, 2022). "Of note, MALAT1 expression levels were increased in docetaxel (DTX)-resistant AR-negative PC3 and DU-145 cells, and DTX-resistant PCa patient tumours, and its overexpression enhanced DTX-chemoresistance in vivo." (PMID 35159022, 2022). "Moreover, the tumor suppressor function of RBM24 appears to be mediated by miR-25, which is the most upregulated miRNAs in RBM24-induced cells and suppresses NPC progression by targeting the oncogenic lncRNA MALAT1 (metastasis associated with lung adenocarcinoma transcript 1) for degradation." (PMID 35406615, 2022). "RES’s suppressive effects on tumor cell migration and invasion and protein expression of β-catenin, c-Myc, and MMP-7 were attenuated by overexpression of MALAT1." (PMID 36552560, 2022). "The results of correlation of marker expression with clinicopathological characteristic of the studied TNBC showed that MALAT1 and BACH1 expression (positivity) is correlated with size of the tumor, nodal metastasis, and TNM stage (p < 0.001)." (PMID 35096427, 2022). "There are two major categories of lncRs, which are defined as oncogenic lncRs such as MALAT1, HOTAIR, SOX2-OT and H19, and tumor suppressing lncRs such as MEG3, PANDAR, GAS5, and TUG1 according to their pathological features." (PMID 36552560, 2022). "In the present work, we observe that MALAT1 targeting broadly hurts the cholinic phenotype via the downregulation of CHKA and PCho synthesis, with essential consequences on tumor cell proliferation." (PMID 35740569, 2022). "This phenomenon is explained mechanistically by the high expression of MALAT1 in senescent cells, which drives ADAM10 expression through the MALAT1/miR-92a/ADAM10 axis and the release of the ligand MICA/B from tumor cell membranes via hydrolysis." (PMID 35309907, 2022). "By promoting β-catenin expression, MALAT1 activates the canonical Wnt signaling pathway and contributes to the formation of HCC tumor sphere, as well as the increase in CD133+ and CD90+ HCC cell populations." (PMID 36685103, 2022).
tumor (continued). "In the analysis of the relative expression level of the tested long non-coding RNA H19, MALAT1 and gene BCL2 we obtained statistically significant levels when comparing tumor versus normal adjacent samples." (PMID 35723379, 2022). "Increased expression of MALAT1 in PCa correlated with Gleason score, PSA, tumor stage and castration-resistant PCa." (PMID 36551531, 2022). "MALAT1 has been observed that interacts with SFPQ, releases PTBP2 from the SFPQ/PTBP2 complex (SFPQ-detached PTBP2), and accelerates tumor growth and metastasis." (PMID 35305641, 2022). "Chemotherapy-induced senescence upon MALAT1 knockdown similarly inhibited MICA/B secretion and enhanced NK sensitivity, demonstrating the potential clinical value of clearing senescent tumor cells." (PMID 35309907, 2022). "The differences in levels of JMJD2C, MALAT1 in NSCLC tumor tissues and para-tumor tissues were assessed by RT-qPCR." (PMID 35046387, 2022). "A large number of studies have reported that targeted inhibition of DANCR, SLCO4A1-AS1, Linc00337, SNHG7/20, NEAT1, MALAT1, ES1 or MALAT1 can reduce the degree of malignancy of tumours at the cellular level and even in animal models." (PMID 35907897, 2022). "It was also demonstrated that DANCR mediated apoptosis by modulating MALAT1, with the expression of MALAT1 being downregulated upon DANCR knockdown in both cell lines and xenograft tumour tissues." (PMID 33807355, 2021). "Our final panel consisted of seven up‐regulated DElncRNAs (CCAT1, CCAT2, H19, HOTAIR, HULC, MALAT1, PCAT1), which were also known as oncolncRNAs and three down‐regulated lncRNAs (MEG3, PTENP1, and TUSC7) as tumor suppressor lncRNAs (tslncRNAs)." (PMID 33094859, 2021). "These caveats are epitomized in a recent analysis of noncoding somatic drivers in 2583 cancer whole genomes from 27 tumor types, which found that several significant noncoding elements, such as NEAT1 and MALAT1, harbored recurrent indels." (PMID 33807183, 2021). "In the terms of MALAT1 expression in tumor patients, most of the published papers showed the overexpression of MALT1 in tumor samples." (PMID 34308750, 2021). "For instance, for MALAT1, NEAT1, and TUG1, both oncogenic and tumor suppressor effects have been reported." (PMID 34322395, 2021). "HOTAIR, HOTTIP, MALAT1, and PVT1 are the most studied oncogenic lncRNA in PDAC, while LINC00673 and H19 are potential tumor suppressors." (PMID 34198989, 2021). "Transcriptome analysis revealed that platinum resistant tumors exhibited lower bulk tumor EZH2 expression with low CARM1 (and high MALAT1) co-expression." (PMID 34140011, 2021). "In fact, MALAT1 acts as a ceRNA to hinder miR-509 and activate the RAC1/JNK pathway, thus promoting OS cell proliferation and tumor progression." (PMID 33920083, 2021). "In contrast, lncRNA MALAT-1 and HULC were found up-regulated in HCC and promote tumor growth, metastasis and drug resistance by interacting with several pathways closely relevant in HCC progression." (PMID 34285143, 2021). "MALAT1 was found overexpressed in GBC tissue samples versus controls and its upregulation correlated positively with tumor size and lymph node metastasis, while also correlating negatively with overall survival." (PMID 34575316, 2021). "The authors showed that overexpression of certain lncRNAs (e.g., MALAT1, MINCR, ROR, LINC00152, and AFAP1-AS1) can be used as potential predictors of worse survival or can be involved in the regulation of tumor size (e.g., AFAP1-AS1, MALAT1 and ROR)." (PMID 34575316, 2021). "In other tumours, METTL3-methylated regulates the MALAT1-miR-1914-3p-YAP axis and increases YAP activity to enhance drug resistance and metastasis." (PMID 35004679, 2021). "This study intends to systematically evaluate the prognostic significance of lncRNA MALAT-1 expression for NSCLC so as to provide evidence-based medical reference for further study of MALAT-1 and development of new tumor markers at the early stage." (PMID 34858541, 2021).
tumor (continued). "MALAT1 is highly expressed in PTC, as an oncogene to promote tumor EMT, and as a tumor suppressor gene to inhibit tumorigenesis in poorly differentiated and anaplastic thyroid carcinoma." (PMID 34930256, 2021). "More recently, MALAT1 has been correlated with the expression of miR-124 and an increased expression of the ZEB2 gene, which regulates the cell proliferation and tumor progression in GBM." (PMID 35004666, 2021). "Therefore, MALAT1 might play a vital role in tumor prognosis and immune regulation." (PMID 34308750, 2021). "MiRNAs can combine with lncRNAs, such as MALAT1, to inhibit large tumor suppressor 2 (LATS2) to regulate the growth, invasion and metastasis of tumor cells." (PMID 34616746, 2021). "MALAT1 can competitively bind to SFPQ leading to PTBP2 release from the SFPQ/PTBP2 complex, which enhances the function of PTBP2 in promoting tumor cell proliferation and migration." (PMID 34778078, 2021). "In NSCLC tissues, patients with high MALAT-1 expression are more likely to develop LNM, large tumor size, tumor differentiation, and TNM stage." (PMID 33052949, 2020). "LncRNA-MALAT1 expression is also dramatically increased in HCC cells in response to hypoxic conditions, whereas knock-down of MALAT1 counteracts the tumor-promoting effect of hypoxia." (PMID 32670881, 2020). "MALAT1 is highly expressed in PDAC tissues and positively correlates with tumor size, clinical stage, lymph node metastasis, distant metastasis and prognosis." (PMID 32257946, 2020). "Patients overexpressing putative oncogenes MALAT1 and TUG1 in MIBC tissue presented prolonged survival, suggesting tumor suppressive effects of both lncRNAs." (PMID 33235218, 2020). "The relationship between the expression of MALAT-1 and the clinicopathological parameters of NSCLC was analyzed from nine aspects: gender, age, tumor size, LNM, tumor differentiation, TNM staging, number of tumors, vascular invasion, and recurrence." (PMID 33052949, 2020). "In BRCA, lncRNAs are emerging as master regulators in tumor biology, and have oncogenic and tumor suppressor functions related to initiation and cancer progression, some examples are HOTAIR, MALAT-1, lincRNAp21, and GAS5." (PMID 32753692, 2020). "The higher expression of MALAT1 was detected in PBMC and in ASC-EV after direct stimulation with TEC-EV, as well as in PBMC and tumor cells after stimulation with ASCind-EV." (PMID 33015029, 2020). "Increased MALAT1 expression in IDH1/2 wild-type primary GBs correlated with patient age and tumor localization (p = 0.032 and p = 0.025, respectively)." (PMID 31479414, 2020). "LncRNAs can function either as oncogenes (e.g., HOTAIR, MALAT1, H19) or as tumor suppressors (e.g., HOTAIRM1, NKILA, XIST) by targeting genes that foster or prevent tumor development and progression, respectively." (PMID 33049922, 2020). "A previous in vivo study has demonstrated that MALAT1-targeted lentiviral shRNA inhibited tumor ontogenesis in heterograft models of HCC cells transformed by arsenite, enhancing the effects of MALAT1 on carcinogen-induced oncogenesis." (PMID 32435156, 2020). "In this regard, MALAT1 was found upregulated in HCC, contributing to tumor development and progression, as well as identified in HCC-derived exosomes." (PMID 32183400, 2020). "LncRNA MALAT1 counted in triggering tolerance of LSCC against chemo‐drugs by boosting metastasis and depressing apoptosis of tumor cells." (PMID 31837057, 2020). "The results showed that the expression of MALAT1, LINC00943 and LINC00261 was significantly higher in the tumour tissues than in the healthy tissues (p = 0.0243, p = 0.0005, p < 0.0001, respectively)." (PMID 32993558, 2020). "In this context, treatment with MALAT-1 specific ASO decreased the size and the number of tumor nodules in a pulmonary metastasis model of human lung cancer." (PMID 32429207, 2020).
tumor (continued). "miR-129-5p, a downstream target gene of lncRNA MALAT1, targeting regulates downstream transcription factor HMGB1 and participates in OS cell proliferation and tumor progression." (PMID 32953888, 2020). "MALAT1 in turn induces ZEB1 through miR-204 down-regulation to enhance the malignancy and invasion of tumor cells via EMT induction." (PMID 32664703, 2020). "MALAT1 was found to enhance the expression of ZEB1 through miR-143-3p down-regulation, resulting in elevated migration and metastasis of tumor cells." (PMID 32664703, 2020). "For instance, H19, HOTAIR, MALAT1, TUG1, GAS5, and CCAT1, were found to play important roles in tumor initiation and development 44-49." (PMID 32922554, 2020). "What's more, the team of researchers demonstrated in vitro experiments that after knocking down MALAT‐1 in the NSCLC cell line, the growth and proliferation of tumor cells were inhibited, and the apoptosis of tumor cells was promoted." (PMID 32779402, 2020). "In pancreatic cancer, MALAT1 showed extremely high expression pattern, leading to increased expression of YAP and decreased LATS1 expression, thus accelerating the tumour growth both in vitro and in vivo." (PMID 32779318, 2020). "With regard to clinicopathological outcomes, high expression of AFAP1-AS1, MALAT1 and ROR corresponded to a large tumor size." (PMID 31297033, 2019). "The GBC-SD cells transfected with the sh-MALAT1 alone or with sh-ABI3BP vector were inoculated in nude mice, with the tumor volume and weight of the nude mice analyzed and compared accordingly." (PMID 31174563, 2019). "Although MALAT1 has been proven to be of the most significant lncRNAs that regulates various tumour types, little information regarding the relationship between TNC and MALAT1 is available." (PMID 31649319, 2019). "The results revealed that the tumor volume and weight in the sh-MALAT1 + sh-ABI3BP-treated mice was significantly elevated when compared with the sh-MALAT1-treated mice (p < 0.05)." (PMID 31174563, 2019). "Studies have found that many lncRNAs, including lncRNA-ROR, MALAT1, and GAS5, can affect tumor development by acting as ceRNAs." (PMID 31186629, 2019). "High expression levels of lncRNA AFAP1-AS1, MALAT1 and ROR were positively correlated with tumor size." (PMID 31297033, 2019). "Therefore, MALAT1 might have multiple regulatory mechanisms for the metastasis of tumor cells." (PMID 30683807, 2019). "The results indicated that increased expression of AFAP1-AS1, MALAT1 and ROR was significantly correlated with large tumor size, and overexpression of LET, LINC00152 and HEGBC indicated advanced T status." (PMID 31297033, 2019). "Next, we demonstrated that MALAT1 promoted GBM proliferation and progression in vitro, and knockdown of MALAT1 reduced tumor volume and significantly prolonged survival in an orthotopic mouse model." (PMID 31648104, 2019). "Furthermore, MALAT1 regulates proliferation, migration, and promotes tumor growth and metastasis in nude mice, this regulation could be through SFPQ and AKAP-9 as MALAT1 interact with SFPQ, hence releasing PTBP2 from the SFPQ/PTBP2 complex, facilitating cell proliferation and migration." (PMID 31632922, 2019). "The roles of MALAT1, EZH2 and ABI3BP in the development of GBC were further explored through xenograft tumor in nude mice." (PMID 31174563, 2019). "Actually, numerous lncRNAs function as oncogenes or tumor-suppressor genes, which were reported to be involved in metastasis and prognosis of HCC, such as MEG3, GAS5, HOTAIR, HULC, H19, and MALAT1." (PMID 31500187, 2019). "Since then, emerging lncRNAs such as MALAT1, TUG1, and UCA1 had been demonstrated to be tumor markers or prognostic indicators of BC26." (PMID 29445179, 2018). "MALAT1 overexpression promoted CRC cell proliferation, invasion and migration in vitro, and stimulated tumor growth and metastasis in mice." (PMID 29739426, 2018).
tumor (continued). "In future studies, efforts should be paid to verify whether MALAT1 really gets involved in regulation of host immunocompetence and whether genetic interventions with MALAT1 is likely to strengthen the effectiveness of host immune systems for killing tumor cells." (PMID 29416769, 2018). "Later, the same group showed that high MALAT-1 expression correlated with high Gleason score, PSA, tumor stage and castration-resistant prostate cancer (CRPC)." (PMID 29755696, 2018). "MALATI promotes tumor growth, invasion, and metastasis of HCC as a decoy lncRNA through the MALAT1/miR-143-3p/ZEB1 axis and inhibiting miR-146b-5p." (PMID 30105249, 2018). "Particularly, MALAT1 has been identified as a functional downstream target of Protocadherin 10 (PCDH10), a tumour suppressor protein, down-regulated in EEC." (PMID 30037059, 2018). "The expression of MALAT1 increased during tumorigenesis and metastasis and promoted the occurrence, proliferation and migration of epithelial-mesenchymal transition (EMT) in tumor cells." (PMID 29435112, 2018). "Several exosomal lncRNAs, such as MALAT-1, linc-POU3F3, ZFAS1, promote tumor growth and migration, prevent tumor cell apoptosis, or induce angiogenesis." (PMID 29456536, 2018). "Interestingly, both STAT3 and MALAT1 over-expression occurred commonly in the tumor, and presumably such a co-occurrence might lead to tumor malignant transformation, it is likely that MALAT1 might act as a downstream effector of STAT3 in accelerating tumor progression." (PMID 30591689, 2018). "More specifically, 4 lncRNAs (CCAT1, CCAT2, HOTAIR, and UCA1) were upregulated, while 2 lncRNAs (MALAT1 and TUG1) and 1 circRNA (CDR1AS) were downregulated in CRC tumor tissues compared to NATs." (PMID 30195762, 2018). "Silencing of MALAT1 inhibited autophagy via HuR-TIA-1-mediated autophagic activation, thus inhibiting tumor proliferation and metastasis in vivo." (PMID 30266744, 2018). "In this light, Cao and colleagues demonstrated that MALAT1 inhibited cell viability by down-regulating miR-155 and promoting FBXW7 expression, a tumor suppressor promoting the degradation of substrates with oncogenic activity such as Cyclin E, c-Myc and AURKA." (PMID 29739426, 2018). "Either high expression of HOTTIP, LINC00152, LINC00673, MALAT1 and UCA1, or low expression of AC007392.4, MEG3 and NKILA is found in tumor tissues." (PMID 29416703, 2018). "Accumulating evidence demonstrated that lower OS rate, poorer TNM stage, larger tumor size and metastasis in patients with hilarcholangiocarcinoma (HCCA) are correlated with the high expression levels of MALAT1." (PMID 29299179, 2017). "In summary, our results provide evidence that Cy5.5 labelling of MALAT1 ASO is a convenient approach and that these novel optical probes can serve as specific optical probes for the in vivo imaging of tumours expressing MALAT1." (PMID 29156758, 2017). "Among the 6 studies that reported lncRNAs function as tumor oncogenes and used tumor weight as the major outcome measure, 5 different lncRNAs (HOTAIR, TUG1, BCAR4, MALAT1 and FGFR3-AS1) were reported." (PMID 29245999, 2017). "Even further, we detected MALAT1, miR-144-3p and ROCK1/ROCK2 expression in the formatted subcutaneous tumor nude mice specimens." (PMID 28938647, 2017). "We also highlighted common long non-coding RNA molecules such as HULC, HOTAIR, MALAT1, XIST, H19 and GAS5, which mediate the two-way interactions between stroma and tumor." (PMID 28392501, 2017). "Expression of the seven lncRNAs UCA1, MALAT1, H19, GAS5, TUG1, ncRAN (SNHG16) and linc-UBC1 (BLACAT) was measured by RT-qPCR in UC tissue set 1 consisting of 106 tumor tissues and 10 benign tissues obtained from radical cystectomies." (PMID 28430799, 2017). "Simultaneously, serum MALAT1, AFAP1-AS1 and AL359062 have potential clinical values for forecasting tumor progression and predicting the therapeutic efficacy for NPC." (PMID 28467811, 2017).